WDR77 (WD repeat domain 77)
Diseases named in the same sentence as WDR77 in open-access papers:
WDR77 is named in the same sentence as 45 diseases in open-access papers, as found by Europe PMC text mining. Sharing a sentence is not in itself a finding about the gene and the disease. The quoted sentences say what the papers report.
breast carcinoma (13 papers, 2013 to 2025). "This function is conserved in other cancers; for instance, in breast cancer, WDR77 drives G1/S phase transition after being stabilized by HNRNPC." (PMID 41425556, 2025). "PRMT5 and WDR77 are upregulated in a number of human cancers, including breast cancer, pancreatic cancer, glioblastoma, and lung cancer, and associated with poor survival, underscoring their essential role in oncogenesis." (PMID 39594744, 2024). "PRMT5 and its substrate-binding partner WDR77 regulate alternative splicing through methylation of ZNF326 in breast cancer." (PMID 32392182, 2020). "In lung squamous cell carcinoma and breast carcinoma cells, protein arginine methyltransferase 5 (PRMT5) complexes with MEP50/WDR77, and WDR5 is recruited by the protein complex to target gene promoters, resulting in histone H3K4 trimethylation, target gene transcription and cancer cell invasion." (PMID 30488017, 2018).
lung carcinoma (7 papers, 2016 to 2025). "Silencing WDR77 or PRMT5 expression in lung cancer A549 cells induced expression of GLPIR1 revealed by DNA microarray (GSE56757) and RT-PCR analyses." (PMID 26988096, 2016). "In searching for genes that mediate PRMT5 and WDR77 functions in lung cancer cells, we performed DNA microarray analysis (GSE56757) with lung adenocarcinoma A549 cells expressing WDR77 or PRMT5 shRNA and found that the loss of WDR77 or PRMT5 expression significantly up-regulated GLIPR1 expression." (PMID 26988096, 2016). "This study reveals a novel pathway that PRMT5/WDR77 regulates GLIPR1 expression to control lung cancer cell growth and GLIPR1 as a potential therapeutic agent for lung cancer." (PMID 26988096, 2016). "In contrast, lung cancer samples express high levels of PRMT5, WDR77, ErbB2, ErbB3 and FGFR3 and decreased levels of GLIPR1, Leprel1 and BTG2." (PMID 27480244, 2016). "But additional gene products that interact genetically or biochemichally with PRMT5 and WDR77 in the control of lung cancer cell growth are not characterized." (PMID 26988096, 2016). "More important, PRMT5 and WDR77 were re-activated in lung cancers and the small hairpin RNA (shRNA)-mediated silencing of PRMT5 or WDR77 expression strongly inhibited growth of lung cancer cells in the tissue culture and abolished growth of lung tumor xenografts in the nude mouse." (PMID 26988096, 2016).
prostate carcinoma (7 papers, 2011 to 2025). A carcinoma that arises from epithelial cells of the prostate gland. "METTL23 has been validated as a prognostic marker in prostate cancer, and the coactivation properties of WDR77 on the androgen receptor have been linked to ovarian cancer." (PMID 38132437, 2023). "We previously identified a novel AR cofactor, p44/WDR77, which specifically enhances AR transcriptional activity in the prostate gland and prostate cancer." (PMID 23755100, 2014). "PRMT5 physically interacts and forms a complex with p44/MEP40/WD45/WDR77 in various cells, including prostate cancer cells, and co-localized with p44 in the cytoplasm of prostate cancer cells." (PMID 22952863, 2012). "Nuclear import of isolated NLS signals is defective in AR-positive prostate cancer (LNCaP and 22RV1) cells, leading to sequestering of p44/WDR77 into cytoplasm and relieve p44/WDR77-mediated growth inhibition." (PMID 21789256, 2011). "Translocation of p44/WDR77 from the nucleus to the cytoplasm occurs in prostatic intraepithelial neoplasia and prostate cancer lesions." (PMID 21789256, 2011). "While p44/WDR77 is resident in the nucleus of benign prostate epithelial cells, it localizes to the cytoplasm in prostate cancer cells." (PMID 21789256, 2011). "Three identified NLS were not functional in AR-positive prostate cancer (LNCaP and 22RV1) cells, which led to localization of p44/WDR77 in cytoplasm." (PMID 21789256, 2011). "We further found that p44/WDR77 NLS signals are not functional in AR-positive prostate cancer cells, resulting in accumulation of p44/WDR77 in the cytoplasm of such cells." (PMID 21789256, 2011).
lung adenocarcinoma (2 papers, 2016 to 2020). A carcinoma that arises from the lung and is characterized by the presence of malignant glandular epithelial cells. "Downregulation of WDR77 arrests growth and differentiation of lung epithelial cells while its upregulation promoted terminally differentiated cells to undergo a new stage of cell proliferation, triggering lung adenocarcinoma formation." (PMID 33175867, 2020).
melanoma (2 papers, 2013 to 2025). A malignant, usually aggressive tumor composed of atypical, neoplastic melanocytes. "Although WDR77 has been implicated in various malignancies, its specific role in the pathogenesis of melanoma is still unclear." (PMID 41425556, 2025). "Next, our analysis strongly linked WDR77 expression to cell cycle dysregulation in melanoma." (PMID 41425556, 2025). "In conclusion, this study establishes WDR77 as both a prognostic marker and functional regulator in melanoma." (PMID 41425556, 2025). "Based on these results, WDR77 has been determined as a key contributor to the invasive phenotype of melanoma." (PMID 41425556, 2025). "Through multi-resolution validation including single-cell and spatial transcriptomics, combined with functional experiments, we demonstrated that WDR77 promotes melanoma progression through cell cycle regulation." (PMID 41425556, 2025). "WDR77 serves as both a prognostic biomarker and functional regulator in melanoma, highlighting its potential as a therapeutic target." (PMID 41425556, 2025). "In melanoma, WDR77 expression negatively correlates with CD8+ T cell recruitment and high WDR77 promoter methylation associated with the improved survival." (PMID 41425556, 2025). "We found that WDR77 expression was correlated with immune cell infiltration levels in melanoma estimated by multiple computational algorithms." (PMID 41425556, 2025). "At the protein level, immunohistochemistry using three different antibodies (HPA026437, HPA026448, and HPA027271) consistently demonstrated elevated WDR77 expression in melanoma compared to normal skin." (PMID 41425556, 2025). "Then, as an essential cofactor of PRMT5, WDR77 was selected as the most prognostically significant gene, prompting comprehensive study into its role in melanoma pathogenesis." (PMID 41425556, 2025). "Compared with normal skin tissues, the expression of WDR77 in melanoma tissues increased significantly (P < 0.05)." (PMID 41425556, 2025). "Experimental verification in Mewo melanoma cells confirmed the nuclear localization of WDR77." (PMID 41425556, 2025). "We observed co-upregulation of WDR77 and PRMT5 in melanoma, suggesting that patients with high WDR77 expression may benefit from PRMT5-targeted therapies currently under clinical evaluation." (PMID 41425556, 2025). "Importantly, single-cell analyses demonstrated that WDR77 is commonly expressed in malignant cells of various cancer types, and this pattern was also observed in melanoma-specific datasets." (PMID 41425556, 2025). "WDR77 knockout led to G1 phase accumulation and increased apoptosis in melanoma cells." (PMID 41425556, 2025). "After that, we investigated the central role of WDR77 in melanoma pathogenesis." (PMID 41425556, 2025). "Thus, we began by examining its expression, and found that at the level of mRNA and protein, the expression of WDR77 in melanoma was significantly higher than that of normal skin tissue." (PMID 41425556, 2025). "Pan-cancer single-cell data showed that WDR77 and CDC20 are co-expressed, which was confirmed in two melanoma-specific datasets." (PMID 41425556, 2025). "Also, WDR77 expression showed negative associations with CD8+ T cell recruitment in melanoma." (PMID 41425556, 2025). "Also, our analysis results demonstrated positive relations between WDR77 and CDC20 in melanoma before we thoroughly examined their functional relationship in melanoma progression." (PMID 41425556, 2025). "We found that both WDR77 and PRMT5 are upregulated in melanoma." (PMID 41425556, 2025).
atopic dermatitis (1 paper, 2025). "Besides, WDR77 was found to be upregulated in cutaneous squamous cell carcinoma, atopic dermatitis, and psoriasis compared to non-lesional skin." (PMID 41425556, 2025).
colon cancer (1 paper, 2024). "SIRT7 also deacetylates WD repeat domain 77 (WDR77) and thereby disrupts the interaction between WDR77 and protein arginine methyltransferase 5 (PRMT5), protecting against proliferation and migration of colon cancer cells." (PMID 37676263, 2024).
endocrine cancers (1 paper, 2025). "Our integrated structural and transcriptomic analyses establish MEP50 (WDR77) as a critical driver of oncogenic programs in endocrine tumors." (PMID 40919714, 2025).
glioma (1 paper, 2025). A benign or malignant brain and spinal cord tumor that arises from glial cells (astrocytes, oligodendrocytes, ependymal cells). "However, WDR77 has clear links to glioma since it is overexpressed in higher-grade and mesenchymal gliomas and is co-expressed with genes involved in cell cycle, metabolism, and immune regulation in glioma cohorts; therefore, it correlates with worse survival outcome." (PMID 41300918, 2025).
head and neck squamous cell carcinoma (1 paper, 2024). A squamous cell carcinoma that arises from any of the following anatomic sites: lip and oral cavity, nasal cavity, paranasal sinuses, pharynx, larynx, and salivary glands. "Our findings demonstrate that upregulation of PRMT5 and WDR77 correlates with the poor survival of head and neck squamous cell carcinoma (HNSCC) patients." (PMID 39594744, 2024).
hepatitis B (1 paper, 2021). "Clinically, Western blot analysis validated that the protein levels of WDR77 and H4R3me2s were lower in the HBx-positive liver biopsy samples from hepatitis B patients." (PMID 34373747, 2021).
virus infection (1 paper, 2023). "Furthermore, MEF cells deficient in Wdr77 displayed increased MAVS aggregation upon viral infection, indicating a conserved inhibitory mechanism of WDR77 in antiviral signaling from mouse to human." (PMID 37563140, 2023). "In response to virus infection, WDR77 is recruited to MAVS to prevent the formation of its prion-like aggregates and thus downregulate RIG-I-MAVS signaling in cells." (PMID 37563140, 2023). "We then went to examine how the interaction between MAVS and WDR77 is modulated during viral infection." (PMID 37563140, 2023). "Furthermore, our study showed that WDR77 is recruited to MAVS upon virus infection and prevents the formation of MAVS prion-like filaments, indicating its critical role in regulating IFN-β induction." (PMID 37563140, 2023). "Additionally, the potential involvement of dysregulated WDR77 in virus infection-related diseases remains to be determined." (PMID 37563140, 2023). "Furthermore, we examined the interaction between MAVS and WDR77 at different time points post virus infection." (PMID 37563140, 2023). "We next investigated the role of WDR77 in the regulation of MAVS aggregation over time, and we performed a time course analysis of MAVS aggregation following virus infection." (PMID 37563140, 2023). "Through direct protein-protein interaction, WDR77 represses the prion-like aggregation of MAVS, thereby negatively regulating MAVS activity after viral infection." (PMID 37563140, 2023). "Furthermore, immunofluorescence analysis showed that WDR77 colocalizes with MAVS in cells, and the interaction between WDR77 and MAVS was enhanced upon virus infection." (PMID 37563140, 2023). "On the other hand, the interaction between WDR77 and TRAF3 was not influenced by virus infection." (PMID 37563140, 2023).
Wilms’ tumour (1 paper, 2024). "This spliceosomal vulnerability likely extends to other components of the spliceosomal machinery such as HNRNPA1, RBM39 and SNRPD3, as well as other cancers such as Wilms’ tumour, where our transcriptomic analyses revealed MYCN regulation of spliceosome regulators including SNRPD1 and WDR77." (PMID 39313128, 2024).
cancer (30 papers, 2013 to 2025). A tumor composed of atypical neoplastic, often pleomorphic cells that invade other tissues. "ß-catenin, MafB, and WDR77 have all been linked to cancer, and they are important for breast cellular transformation in our Src-inducible model." (PMID 35482762, 2022). "Our study suggests that dysfunction of WDR77 could lead to inflammation, which may contribute to the development of cancer since chronic inflammation is known to be a potential cause of tumor growth." (PMID 37563140, 2023). "Next, Spearman correlation analysis across 189 pan-cancer single-cell datasets revealed a positive correlation between WDR77 and CDC20 (r = 0.42, P < 0.001)." (PMID 41425556, 2025). "WDR77 was predominantly expressed in malignant cells across pan-cancer datasets and positively correlated with CDC20." (PMID 41425556, 2025). "Across pan-cancer cell lines, WDR77 knockout resulted in cell growth arrest or apoptosis." (PMID 41425556, 2025). "In pan-cancer, WDR77 was preferentially highly expressed in malignant cells." (PMID 41425556, 2025). "In summary, our results not only shed light on the mechanism by which WDR77 inhibits prion-like aggregation of MAVS to suppress IFN-β induction in antiviral immune response but also provide insights into the clinical relevance of WDR77 in cancer biology." (PMID 37563140, 2023). "Overexpression of WDR77 stimulates tumorigenesis in breast and other cancer types." (PMID 35482762, 2022). "Both PRMT5 and WDR77 are essential for growth of lung epithelial and cancer cells." (PMID 26988096, 2016). "Similarly, SIRT7 was found to counteract cancer development by the deacetylation of WDR77." (PMID 35136826, 2022). "Protein arginine methyltransferase 5 (PRMT5) complexed with methylosome protein 50 (MEP50)/WD repeat domain 77 (WDR77) can catalyze H3 and H4 arginine methylation, leading to the activation of EMT markers and carcinoma cell metastasis." (PMID 34298613, 2021). "Three recent studies have reported an increased dependency of cancer cells harboring a homozygous deletion of the MTAP gene on PRMT5, WDR77 and RIOK1, all members of a PRMT5 containing complex, and the upstream component MAT2A." (PMID 29983885, 2018). "WDR77 and PRMT5 are ubiquitously re-expressed in lung hyperplasia and cancer and conversely, GLIPR1 expression is significantly down-regulated during lung tumorigenesis." (PMID 26988096, 2016). "Thus, it has been shown that in OvCa lncRNA, RP11-552M11.4/lnc-WDR77 (human WD-repeat domain 77) binds to mRNA BRCA2, by suppressing the expression of which it stimulates proliferation, migration, and invasion of cancer cells and suppresses apoptosis." (PMID 33238475, 2020). "Although not present in Case 2, WDR77 and hsa-miR-495-3p were also shown as relevant biological features for most of the groups, which was also identified by other studies as important in cancer or CRC development." (PMID 41401030, 2025).
tumor (19 papers, 2013 to 2026). "These core genes—TRAF4, UBE2L3, FBXO45, UBE2L6, FBXL14, SKP2, CHAF1B, and WDR77—have been implicated in tumor progression in previous studies." (PMID 40990020, 2025). "Clinically, PRMT5 and WDR77 expression in tumor-infiltrating T cells are negatively correlated with PDCD1 expression and renders tumors resistant to PD-1-targeted immunotherapy." (PMID 41623183, 2026). "E2F8, WDR77, and hsa-miR-495-3p stood out as biological features, while pathological stage, age, new tumor event, lymph node count, and chemotherapy have shown themselves as interesting clinical features." (PMID 41401030, 2025). "Among these features, seven were clinical: pathological stage, new tumor event, age, number of lymph nodes, chemotherapy, number of positive lymph nodes, and ethnicity; and four were biological features: hsa-miR-495-3p, WDR77, E2F8, and APCDD1." (PMID 41401030, 2025). "Close correlations were observed between WDR77 and CDC20, WDR77 and tumor cells, and CDC20 and tumor cells." (PMID 41425556, 2025). "Weekly BLI TBL2 Acts as a Scaffold to Promote the Interaction Between PRMT5 and WDR77(Bioluminescence imaging) showed higher tumor loads in the TBL2‐overexpression group and lower tumor loads in the TBL2‐silenced group." (PMID 39499734, 2024). "Our analysis revealed significant upregulation of both PRMT5 and WDR77 mRNA levels in tumor samples compared to normal samples from patients with HNSCC." (PMID 39594744, 2024). "A large number of AR coactivators have been described to promote PCa growth, yet we described several AR coactivators, including p44/Mep50/WDR77, with tumor suppressor function in PCa." (PMID 23734213, 2013). "Beyond cell cycle regulation, we found that WDR77 relates to tumor immunity." (PMID 41425556, 2025). "To further determine the effect of depleting PRMT5 and WDR77 in SCC development in the in vivo context, we injected 5 × 104 sgNeg, sgPRMT5, and sgWDR77 cells subcutaneously into nude mice to generate tumor xenografts." (PMID 39594744, 2024). "Among the genes significantly co-activated in G3 basal-like tumor samples, we identified 3 reproducible and concordantly up-regulated SAGPs (ABI1/PDSS1, DIS3/BORA and WDR77/ATP5F1)." (PMID 26517092, 2015). "The biomarkers (RNASeq-derived) LRRC41, UBA2, and WDR77 are more expressed in IDHmut-non-codel compared to IDHwt, suggesting that such molecules can be part of the tumor development through transcriptional enhancing mechanisms." (PMID 41300918, 2025).
infection (3 papers, 2021 to 2023). The state of being infected such as from the introduction of a foreign agent such as serum, vaccine, antigenic substance or organism. "Our data revealed that trVLP infection of PRMT5 or WDR77 knockdown cells was comparable with that of WT cells." (PMID 37276230, 2023). "As expected, WDR77 significantly regulated the ratio of pgRNA to cccDNA in HBV de novo infection PHH and HepG2-NTCP cells." (PMID 34373747, 2021). "Immunostaining of viral ORF2 antigen by 2G8 antibody suggested that Kernow C1/p6 infection was enhanced upon PRMT5 or WDR77 knockdown, which was also supported by the flow cytometry data as evidenced by increased HEV infection (ORF2 positive cells) upon PRMT5 and WDR77 knockdown." (PMID 37276230, 2023). "Strikingly, Western blot analysis showed that WDR77 knockdown reduced the levels of Rme2sy and H4R3me2s in HBV de novo infection HepG2-NTCP cells." (PMID 34373747, 2021). "Strikingly, our data verified that WDR77 restricted cccDNA transcription and HBV replication in HBV de novo infection PHHs and HepG2-NTCP cells in a PRMT5 methyltransferase activity-dependent manner, leading to the increase of cccDNA-bound H4R3me2s." (PMID 34373747, 2021). "HEK293T cells were transiently transfected with Flag-PRMT5 and Flag-WDR77 with or without infection by Sendai virus (SeV)." (PMID 37563140, 2023). "Interestingly, we found that HBV down-regulated WDR77 in human liver-chimeric mice liver tissues, HBV plasmid transfected HepG2 cells and HBV de novo infection HepG2-NTCP cells." (PMID 34373747, 2021).
WDR77 also shares sentences with these, for which no sentence is quoted: ovarian carcinoma (3 papers); gastric cancer (2); liver cancer (2); lymphoma (2); small cell lung carcinoma (2); squamous cell carcinoma (2); acute lymphoblastic leukaemia (1); adrenocortical carcinoma (1); breast tumor (1); Cachexia (1); cervical cancer (1); colorectal cancer (1); cutaneous squamous cell carcinoma (1); endometrial cancer (1); glioblastoma (1); hepatoblastoma (1); leukemia (1); liver disease (1); lung squamous cell carcinoma (1); metastatic melanoma (1); myeloma (1); non-Hodgkin lymphoma (1); ovarian epithelial tumor (1); pancreatic cancer (1); psoriasis (1); sarcoma (1); skin basal cell carcinoma (1); skin cutaneous melanoma (1); T-cell leukemia (1).